NLRP3 (NLR family pyrin domain containing 3)
Diseases named in the same sentence as NLRP3 in open-access papers (continued):
Sharing a sentence is not in itself a finding about the gene and the disease.
atherosclerosis (continued). "We conclude that NLRP3 plays a key role in promoting the formation and development of atherosclerosis in diabetes." (PMID 35844498, 2022). "Arglabin inhibits the activation of NLRP3 inflammasome in macrophages, thus having an anti-inflammatory effect on atherosclerosis-prone mice by lowering serum levels of IL-1β." (PMID 35563387, 2022). "Highly involved in the development of atherosclerosis and ischemia/reperfusion injury, NLRP3 inflammasome has gained much attention in study of stroke pathogenesis." (PMID 36204568, 2022). "Several other stimuli such as bacterial, viruses, particle matter, and ROS have been identified to be involved in the priming and triggering NLRP3 inflammasome in the process of atherosclerosis." (PMID 36304814, 2022). "Negative regulation of the NLRP3 inflammasome to inhibit pyroptosis is an important research direction for the prevention and treatment of atherosclerosis." (PMID 36006939, 2022). "Taken together, these findings demonstrated that OLFR2 ligation aggravates atherosclerosis progression by triggering NLRP3 inflammasome activation and subsequent proinflammatory IL-1β release." (PMID 35864109, 2022). "Recent research has shown that the NLRP3 inflammasome plays an important role in various metabolic inflammatory diseases, such as atherosclerosis (As) and diabetes." (PMID 35719709, 2022). "Previous studies have alsoshown that the NLRP3 inflammasome promotes atherosclerosis progressionby targeting a series of cellular and molecular components, including STAT, MAPK,JNK, microRNA networks, ROS, PKR, etc.." (PMID 39076616, 2022). "These protective effects were no longer evident in GPR109A −/− and NLRP3 −/− BMDMs, indicating that β-OHB attenuates atherosclerosis via GPR109A-NLRP3 dependent pathway." (PMID 36339405, 2022). "Accumulation of cholesterol crystals in a mouse model of atherosclerosis promotes caspase-1 activation via the NLRP3 inflammasome, triggers IL-1β maturation, and induces pathogenic Th17 differentiation." (PMID 35562903, 2022). "Hypoxia, a driving factor of atherosclerosis, arose in atherosclerotic plaques, which can induce and enlarge NLRP3 inflammasome activation in macrophage." (PMID 36304814, 2022). "Here, we chose to focus on the interaction between gut microbiota with its metabolites (e.g., TMAO and SCFAs) and NLRP3 inflammasome in atherosclerosis." (PMID 36082127, 2022). "For instance, selective NLRP3 inhibitor MCC950 can hinder atherosclerosis development by attenuating inflammatory responses and macrophage activation in ApoE−/− mice and ox-LDL-induced THP-1-derived macrophages." (PMID 36557935, 2022). "The Nod-like receptor pyrin domain-containing protein 3 (NLRP3) inflammasome activation contributes to the vascular inflammatory response driving atherosclerosis formation and progression." (PMID 35811739, 2022). "The persistent activation of NLRP3 promotes the overexpression of inflammatory factors, leading to diabetes, atherosclerosis, gout, and tumor occurrence." (PMID 35873581, 2022). "IL-1β is one of the well-known inflammatory effector molecules during period of NLRP3 inflammasome activation, and also plays a pro-atherogenic role in the progression of atherosclerosis." (PMID 36304814, 2022). "Elevated levels of components of the NLRP3 inflammasome have been found in atherosclerotic plaques and have been shown to play a role in the initiation and progression of atherosclerosis." (PMID 35877579, 2022). "A growing body of evidence demonstrates that the NLRP3 inflammasome and TLRs contribute to the development of atherosclerosis, and are identified to be a promising new target for the treatment of these diseases." (PMID 35459215, 2022).
atherosclerosis (continued). "It involves in the pathogenesis and outcomes of atherosclerosis characterized by NLRP3 inflammasome assembly, membrane pore formation, cell swelling, pro-inflammatory mediator and cytokine release." (PMID 36304814, 2022). "Then, the activated NF-κB further affects the NLRP3 signaling and contributes to the development of atherosclerosis." (PMID 36187801, 2022). "The statins inhibit TLRs and NLRP3 inflammasome to treat atherosclerosis and other cardiovascular diseases (CVD)." (PMID 35078487, 2022). "The development of atherosclerosis in DM has been reported to involve inappropriate persistent inflammation induced by PAMPs and DAMPs overactivation of the NLRP3 inflammasome." (PMID 35844498, 2022). "The expression of NLRP3 in aorta tissue specimens of patients with atherosclerosis has been correlated with the disease’s severity." (PMID 36671400, 2022). "Endothelial injury is the first step of atherosclerosis,whereas expression of NLRP3 and ASC in endothelial cells increases underthe action of nicotine, ultimately causing pyroptosis." (PMID 39076616, 2022). "NLRP3 inflammasome activation helps drive atherosclerosis development and progression of vascular inflammatory responses and is also a major producer of cleaved interleukin (IL)-1 cytokines." (PMID 35296647, 2022). "Previous studies have found that monocytes play a role in the process of atherosclerosis by activating the NLRP3 inflammasome." (PMID 36818726, 2022). "We examined the NLRP3 inflammasome related pathway, playing a pivotal role in atherosclerosis, in EAT, PAT and subcutaneous AT (SAT), their relationship to cell types and anthropometric measures in patients undergoing coronary artery bypass grafting." (PMID 36644557, 2022). "All of these findings reinforce the significant role of NLRP3 and its derived cytokines in the pathogenesis of atherosclerosis." (PMID 35204152, 2022). "Given the NLRP3 inflammasome-mediated inflammation and pyroptosis in the regulation of atherosclerosis, we also confirmed the changes of NLRP3 during atherogenesis." (PMID 36186576, 2022). "Given the known role of NLRP3 inflammasome in atherosclerosis, it is possible that AIM2 promotes the development of atherosclerosis partially through activating the NLRP3 inflammasome." (PMID 35464402, 2022). "Multiple studies have shown that NLRP3 inflammasome, IL-1β, IL-18 and pyroptosis have a decisive and important role in various diseases, such as DM, atherosclerosis, and Alzheimer’s disease." (PMID 35844498, 2022). "Studies in the last few years have demonstrated that NLRP3 inflammatory vesicles play a crucial role in the development of atherosclerosis as well as its complications." (PMID 36589841, 2022). "MicroRNA-30c-5p can inhibit NLRP3 inflammation-dependent endothelial cell pyroptosis by downregulating FOXO3 expression in atherosclerosis." (PMID 35865939, 2022). "Current concepts in the inflammatory concept of atherosclerosis include the atheroprone potential of NLRP3 inflammasome and neutrophil extracellular traps (NETs)." (PMID 36555579, 2022). "Our study provides mechanistic insights into the NLRP3 inflammasome in vascular inflammation and atherosclerosis." (PMID 35641492, 2022). "Over-activated NLRP3 inflammasome was also related to atherosclerosis in diabetic patients, and NLRP3 knockdown reduced and stabilized atherosclerotic plaque in a diabetic atherosclerosis mouse model." (PMID 35204152, 2022). "In conclusion, the serum level of NLRP3 is inversely correlated with Treg/Th17ratio in atherosclerosis." (PMID 39076663, 2022). "Activation of NLRP3 inflammasome has been documented in the pathogenesis of atherosclerosis, and elevated NLRP3 inflammasome levels were recorded in atherosclerotic patients." (PMID 36304814, 2022).
atherosclerosis (continued). "The NLRP3 inflammasome has recently gained attention in atherosclerosis research since crystalline cholesterol and oxLDL were shown to activate this complex." (PMID 36012389, 2022). "For example, to alleviate atherosclerosis, fucoidan (a polysaccharide mainly composed of fucose and sulfate) inhibits NLRP3 activation through SQSTM1/p62-dependent selective autophagy." (PMID 36671400, 2022). "Emerging evidence indicates TMAO accelerates the activation of the nucleotide-binding oligomerization domain leucine-rich repeat proteins 3 (NLRP3) inflammasome in not only atherosclerosis but also UVC." (PMID 35629435, 2022). "In a mouse model of atherosclerosis, testosterone suppresses the NLRP3 inflammasome and inflammation, whereas female sex hormones contribute to NLRP3-induced proinflammatory responses." (PMID 35222363, 2022). "The mechanisms whereby the NLRP3 inflammasome orchestrates atherosclerosis remain to be completely elucidated." (PMID 35641492, 2022). "Further, we provided an overview of the most recent findings regarding the relationship between defective autophagy and NLRP3 inflammasomes in the etiopathogenesis of atherosclerosis." (PMID 36671400, 2022). "NLRP3 inflammasomes centrally integrate multiple signal inputs in different types of cells and in the pathogenesis of atherosclerosis." (PMID 36186576, 2022). "In this review, we summarized recent advances focusing on the role of NLRP3 inflammasome in atherosclerosis, cardiomyopathy, and other common CVDs, and we discussed the therapeutic potential of inhibiting NLRP3 inflammasome." (PMID 36204568, 2022). "The activation of NLRP3 was regulated by PI3K or AKT in atherosclerosis, and MAPK/NLRP3 inflammasome/STAT3 signaling was involved in the neuroinflammatory responses." (PMID 35457254, 2022). "Extensive animal studies have also investigated the role and mechanism of the NLRP3 inflammasome in atherosclerosis." (PMID 36082127, 2022). "NLRP3 inhibitor significantly decreased inflammatory cytokines and inhibited the development of atherosclerosis in ApoE−/− mice." (PMID 35464402, 2022). "Consistent with our findings, inhibition of the NLRP3 inflammasome by the selective inhibitor MCC950 reduces atherosclerosis in ApoE−/− mice." (PMID 34552216, 2022). "Studies conducted in the early 2000s examined the effects of IL-1β and IL-18, downstream cytokines of the NLRP3 inflammasome, on atherosclerosis in mice." (PMID 36082127, 2022). "Our findings provide direct evidence that Nur77 plays an important role in regulating NLRP3 inflammasome and thus represents a promising target for the treatment of atherosclerosis." (PMID 35464766, 2022). "In the context of atherosclerosis progression, NLRP3 inflammasome is triggered by the oscillatory shear forces that act on the endothelium, the cholesterol crystals, oxLDL endocytosis through CD36, extracellular ATP, or uric acid crystals." (PMID 36362423, 2022). "The dysregulation of NLRP3 inflammasomes, and particularly its genetic variations, contribute to atherosclerosis." (PMID 36082127, 2022). "In the coronary tree, upregulation of ASC, caspase-1, and IL-18 was noted in segments with advanced atherosclerosis, together with prevalent NLRP3 inflammasome-positive foam cells around the necrotic core." (PMID 36555579, 2022). "Targeting HDAC6 attenuates nicotine-induced macrophage pyroptosis via the NF-kappaB/NLRP3 pathway in atherosclerosis." (PMID 35910382, 2022). "In contrast, downregulation of FOXO3 reduces NLRP3 inflammasome-mediated endothelial cell pyroptosis in atherosclerosis." (PMID 35085103, 2022). "Synthesizing the current literature as well as research results, we summarized the effects and mechanisms of SGLT2i on the NLRP3 inflammasome in atherosclerosis treatment." (PMID 36589841, 2022).
atherosclerosis (continued). "It is worth noting that IL-1β mediates the activation of NLRP3 inflammasome and the pathogenesis of atherosclerosis." (PMID 36304814, 2022). "Bone marrow transplantation of atherosclerosis-prone mice with TET2-deficient bone marrow resulted in an increase in plaque development, which was associated with increases in NLRP3-mediated IL-1β production in TET2-deficient macrophages." (PMID 36613465, 2022). "Recent results obtained in mice with early atherosclerosis revealed that inhibition of IL-1β and NLRP3 inflammasome reduces leukocyte accumulation in atherosclerotic aortas." (PMID 35310965, 2022). "A vicious cycle of IL-1β-mediated NLRP3 inflammasome activation has also been observed in atherosclerosis and amyloid β formation in patients with Alzheimer’s disease." (PMID 35138513, 2022). "It has been shown that melatonin, as an activator of Nrf2, can inhibit NLRP3 inflammation, reduce atherosclerosis, and improve cerebral ischemia–reperfusion injury by activating Nrf2." (PMID 36139384, 2022). "In basic research, the uremic toxin TMAO is tightly correlated with NLRP3 activation in atherosclerosis and UVC." (PMID 35629435, 2022). "Pyroptosis is closely in relation to the progress of atherosclerosis; Additionally, extensive expression of NLRP3 was observed in ECs, macrophages, and SMCs." (PMID 36304814, 2022). "This study aimed to delve into the mechanism behind the NLRP3 inflammasome in dictating atherosclerosis and to explore the role and mechanism for VX765 in targeting atherosclerosis." (PMID 35641492, 2022). "A protein complex called NLRP3 inflammasome is involved in the release of mature interleukin-1β (IL-1β), which is connected to the initiation and progression of atherosclerosis." (PMID 36671400, 2022). "Given the intimate link between dysregulation of NLRP3 inflammasome and atherosclerosis, it is both challenging and intriguing to reveal the complex mechanisms of regulation and activation of NLRP3 inflammasome and their influence on human health and disease." (PMID 35459215, 2022). "Growing evidence suggests that the NLRP3 inflammasome contributes to the development of DM and atherosclerosis, and that inactivation of NLRP3 inflammation is beneficial for the treatment of these diseases." (PMID 35844498, 2022). "Owing to its critical role in the development of atherosclerosis, NLRP3 is a promising therapeutic target for atherosclerosis." (PMID 35844498, 2022). "NLRP3 inflammasome plays an important role in the occurrence, development and prognosis of many chronic inflammatory diseases, such as atherosclerosis, obesity, diabetes, Tuberculosis, rheumatoid arthritis (RA)." (PMID 34904398, 2022). "Here, we sought to determine that mitochondrial dynamic related lncRNA (MDRL) modulates NLRP3 inflammasome activation and apoptosis of vascular smooth muscle cells (VSMCs) and protects arteries against atherosclerosis." (PMID 36186576, 2022). "Taken together, these studies highlight the important role of IL-1β and the NLRP3 inflammasome in atherosclerosis and mark them as possible targets for the development of new therapeutic strategies." (PMID 35890291, 2022). "Aberrant NLRP3-driven inflammation underpins many chronic degenerative diseases, including type II diabetes, gout, atherosclerosis, inflammatory bowel disease, and AD." (PMID 36127465, 2022). "The classical pyroptosis pathway mediated by the NLRP3 inflammasome is involved in the occurrence and development of atherosclerosis." (PMID 36006939, 2022). "Clinical and basic studyresults have shown that the NLRP3 inflammasome is expressed inendothelial cells, immune cells, smooth muscle cells, and other cells involved inthe pathogenesis of atherosclerosis." (PMID 39076616, 2022). "In early atherosclerosis, macrophage-derived NLRP3 inflammasome suggestsbeneficial effects on plaque stability, which are mediated by their involvementin inflammatory anti-injury reaction." (PMID 39077721, 2022).
atherosclerosis (continued). "Previous studies showed that Trx-1 modulates NLRP3 inflammasome activities during atherosclerosis development." (PMID 35496300, 2022). "Thisstudy is designed to probe the regulative action of serum Nod-like receptorprotein 3 (NLRP3) on the Treg/Th17 balance in patients with atherosclerosis." (PMID 39076663, 2022). "In contrast, endothelial-specific NLRP3 knockout attenuated the severity of atherosclerosis in high-fat diet mice." (PMID 35844498, 2022). "Several studies have demonstrated that the NLRP3 inflammasome and gut microbiota are also involved in the occurrence and development of atherosclerosis via regulating lipid metabolism, inflammation, oxidative stress, and other mechanisms." (PMID 36082127, 2022). "Ethanol activates NLRP3/caspase-1, not only in the cerebral vessel, which leads to early development of atherosclerosis, but also in the brain, which amplifies neuroinflammation." (PMID 36059543, 2022). "Studies have shown that melatonin can improve mitophagy and inhibit NLRP3 inflammasome activation in animal models of subarachnoid haemorrhage and atherosclerosis." (PMID 35983247, 2022). "Future studies should concentrate on the molecular mechanisms of NLRP3-mediated pyroptosis in atherosclerosis and other pyroptosis-related chronic diseases." (PMID 36304814, 2022). "Recently, the excess activation of NLRP3 inflammasome has been confirmed to mediate inflammatory responses and to participate in genesis and development of atherosclerosis." (PMID 35493086, 2022). "In the context of atherosclerosis, CCs are considered a major driver of NLRP3 inflammasome activation." (PMID 35890291, 2022). "Our study provides significant insights into the mechanisms for NLRP3 inflammasome activation in driving atherosclerosis." (PMID 35641492, 2022). "Other therapeutic strategies and current clinical trials targeting the NLRP3 inflammasome for atherosclerosis treatment would be described in the Atherosclerosis Therapies section of this review." (PMID 35459215, 2022). "NLRP3 inflammasome can lead to ischemic stroke by activating inflammatory response and participating in atherosclerosis." (PMID 34526897, 2021). "Several lines of evidence suggest that excessive NLRP3 inflammasome activation is response for several inflammatory disorders, including T2D, atherosclerosis and gout." (PMID 34745110, 2021). "The maturation and release of IL-1β are mainly regulated by the NLRP3 inflammasome, which plays an important role in many inflammatory diseases, such as atherosclerosis and autoimmune diseases." (PMID 33771213, 2021). "The study of C-reactive protein (CRP), interleukin (IL)-1β, and NLR family pyrin domain-containing 3 (NLRP3) inflammasome has revealed critical roles for each in post-infarction systemic inflammation and progression of atherosclerosis." (PMID 34685553, 2021). "In this work, our study uncovers a role of YAP in regulation of the NLRP3 inflammasome activation, and provides potential therapeutic target to treat a number of inflammatory disorders, such as atherosclerosis, gout, colitis and sepsis." (PMID 33976226, 2021). "Atherosclerosis is one type of cardiovascular disease (CVD) in which activation of the NLRP3 inflammasome and toll-like receptor (TLR) pathways is implicated." (PMID 32378144, 2021). "Recently, aberrant NLRP3 inflammasome activation has been shown to be related to the progress of several human diseases, including gout, type 2 diabetes (T2D), atherosclerosis and influenza virus- (IV)-induced inflammation." (PMID 34745110, 2021). "Our present study provides evidence for the involvement of monocytes in triggering NLRP3 inflammasome signaling promoting VSMCs phenotypic switch and atherosclerosis progression." (PMID 35008765, 2021). "Dapagliflozin treatment reduced the production of NLRP3 protein and ROS in aortic tissues, thereby partially reversing the formation of atherosclerosis." (PMID 33754074, 2021).